IL1B (interleukin 1 beta)
Diseases named in the same sentence as IL1B in open-access papers (continued):
Sharing a sentence is not in itself a finding about the gene and the disease.
viral infection (continued). "Interleukin 1 (IL-1) family of cytokines, such as IL-1β and IL-16 are secreted when the NOD-like receptors (NLRs) detect intracellular bacterial and viral infections and induce the inflammasome complex." (PMID 34070595, 2021). "We found that CyPA, induced by virus infection via CD147 receptor, promotes inflammation by upregulating the expression of IL-17, IL-6, and IL-1β in lung epithelial cells." (PMID 34564690, 2021). "The increasing plasma cytokines (IL-1β/2R/6/8/10 and TNF-α) confirmed the cytokine storm following the virus infection." (PMID 33625490, 2021). "As in regular viral infection, BTV12 activated monocytes normally and strongly, indicated by the TNF-α and IL-1β expressions, but activated the Th2 pathway poorly, indicated by the IL-4." (PMID 33375108, 2020). "IRF upregulation induced by Type I and II Interferons, viral infection, LPS in addition to several cytokines including TNF-a, IL-1β, IL6 and IL23." (PMID 33137133, 2020). "The MAPK pathway is activated by many kinds of stimuli including endotoxic lipopolysaccharides (LPS), hyperosmolarity, proinflammatory cytokines and factors such as IL-1β, and PAF and viral infections." (PMID 32014061, 2020). "First, Type II alveolar cells will secrete a host of inflammatory cytokines in response to viral infection such as IL-1β, IL-6, TNF-α, CXCL10, and CCL2 that will act to recruit other inflammatory cells to help abate the viral infection." (PMID 32760409, 2020). "Induction of proinflammatory cytokines such as IL-1β, IL-6, IFN-α, and TNF-α, is indicative of acute viral infection in animals." (PMID 31906555, 2020). "PCT synthesis is stimulated by cytokines such as IL-6, IL-1β, and TNF-α, or directly by lipopolysaccharides and it is downregulated by interferon-γ, which is commonly produced in response to viral infections." (PMID 33419284, 2020). "Cytokines including GM-CSF, IL-2, IL-1β, TNF-α, IFN-γ, and IL-10 are key molecules that regulate innate and adaptive immune responses to viral infection." (PMID 31412594, 2019). "The mRNA expression levels of IL-1β, IL-6, IL-8, IFNs, TNF-α, Mx, and OASL were significantly upregulated during the viral infection." (PMID 31288442, 2019). "We propose that in response to viral infection, mtROS is produced by damaged and depolarized mitochondria leading to NLRP3 activation and antiviral inflammation that is driven by IL-1β and IL-18." (PMID 31229895, 2019). "Other genes that are well-known to be upregulated with early viral infection such as ISG15 and interleukin (IL)-1β were also commonly upregulated on day 1 p.i. along with NADPH oxidase 1 (NOX1)." (PMID 31635289, 2019). "In the process of virus infection and lung damage, the NLRP3 inflammasome pathway is very critical and is closely bound up with IL-1β, IL-33, and IL-18." (PMID 32047436, 2019). "Meanwhile, B4GALT5 up-regulated the expression of IFN-α and inflammatory factors (IL6, IL-18, IL-1β, TNF-α) to resist viral infection." (PMID 29546034, 2018). "We demonstrate that neutrophils recruited into the airways during viral infection release mCRAMP, which subsequently activates the NLRP3 inflammasome in alveolar macrophages and triggers IL-1β release." (PMID 29079611, 2018). "In dendritic cells of patients with COPD, OM-85 increased the secretion of IL-1α, IL-1β, IL-6 and TNF-α, which was regarded as a strengthening of the immune response during viral infection." (PMID 29182620, 2017). "In our study, levels of 12 cytokines and chemokines in the apical supernatant of hAECs were elevated following A(H7N9) virus infection, including GRO-α, MIP1-α, MIP1-β, SDF-1α, RANTES, IL-1α, IP10, IL-1RA, MCP1, IL-8, IL-6, and IL-1β." (PMID 28900138, 2017). "Levels of twelve cytokines and chemokines in the apical supernatant of hAECs were elevated following A(H7N9) virus infection, including GRO-α, MIP1-α, MIP1-β, SDF-1α, RANTES, IL-1α, IP10, IL-1RA, MCP1, IL-8, IL-6, and IL-1β." (PMID 28900138, 2017).
viral infection (continued). "For instance, RIPK1 was shown to be essential in inducing inflammatory cytokines (IL-6, IL-1β, TNF-α) in response to bacterial and viral infections." (PMID 28410401, 2017). "Although Vsig4 deficiency did not seem to affect the basal expression level of these factors before viral infection, qRT-PCR data showed that MHV-3 infection super-induced Vsig4−/− PEMs to express Fgl2, Tnf, Il-1β, and Il-6." (PMID 29109438, 2017). "Many viral infections stimulate TLR- or TNF-α-mediated signaling, resulting in the activation of the NLRP3 inflammasome and leading to the subsequent production of IL-1β and COX-2." (PMID 28445497, 2017). "Both IL-1α and IL-1β levels in the SCD animals were elevated at baseline, similar to levels eventually reached by these cytokines in WT animals after virus infection." (PMID 28256526, 2017). "We observed increased level of inflammatory mediators (IL-1α, IL-1β, IL-6, MIP-1α (CCL3), MIP-1β (CCL4), RANTES (CCL5), MCP-1 (CCL2)) following H5N3 virus infection at 4, 8 and 20 hpi compared to cells infected with the H1N1/WSN, H5N2 and H9N2 viruses." (PMID 28558796, 2017). "Oncolytic herpes simplex virus–resistant Ewing sarcoma tumors that express IL-1β, IL-6, and CXCL1 induce CD11b+ cell expression of VEGF after virus infection." (PMID 28536380, 2016). "Moreover, there are reports that IL-1β contributes to localized inflammation in response to parasitic, bacterial or viral infections, which may be a critical mechanism for fibrogenesis with large increases in production of extracellular matrix (ECM) such as collagens." (PMID 27322427, 2016). "The focus of this review will be on the mechanisms controlling the expression of IL-1β, COX-2, and iNOS, in macrophages during virus infection." (PMID 26295266, 2015). "The activation of PRRs induces the expression of cytokines and antiviral proteins, including IL-1β, IL-2, TNF-α, MX, and OAS, which alert the immune system to viral infection." (PMID 26005441, 2015). "Virus infection in cardiac myocytes initiated the expression of pro-inflammatory cytokines including TNF-α, IL-6, IL-1β and chemokines." (PMID 25728713, 2015). "We next measured levels of immunomodulatory mediators in lung homogenates and report that viral infection in fibrotic lungs (Bleo+MHV-68) led to a significant increase in lung levels of CCL2, IL-1β, TNFα and IL-10 above the levels detected for Bleo lungs." (PMID 26138704, 2015). "Thus we are confident that bacterial and viral infections cause the release of EVs into the airway, and if there are high levels of ATP present in the airway (like in asthma and COPD), it could trigger the release of IL-1β and IL-18." (PMID 24972036, 2014). "Many factors, such as UV radiation, cytokines (e.g., IL-1β, TNF-α, IFN-γ, and IL-15), viral infections (hepatitis B or C, HIV infection) can induce expression of Fas in epidermis." (PMID 22778762, 2012). "Growth kinetics and induction of select immune response genes, including IFN-α and myxovirus-resistance gene I (Mx), as well as proinflammatory cytokines (IL-1β and IL-6), were measured in response to chicken IFN-α and viral infection over time." (PMID 21939525, 2011). "Specifically, spermine has been shown to reduce IL-1β in acute liver injury, suppress NLRP3 inflammasome activation in diabetic atherosclerosis, and downregulate Guanylate Binding Protein 5 (GBP5)-mediated NLRP3 activation during viral infection." (PMID 41463524, 2025). "Sendai virus and influenza A virus were the earliest viruses to be studied for their ability to activate caspase-1 through NLRP3, thereby promoting the production of IL-1β and IL-18, which provided evidence for the involvement of the NLRP3 inflammasome in the viral infection response." (PMID 40906404, 2025).
viral infection (continued). "The resulting network revealed a highly interconnected core centered around key cytokines—including IL-6, IL-1β, IL-10, TNF-α, IL-18, and GM-CSF—which function as pivotal hubs driving the host inflammatory response and immunopathogenesis in both viral infections." (PMID 41366310, 2025). "In the current study, an intense immunoexpression of IL-1β and TNF-α was also observed in the acinar and GCT cells of the infected SMGs, confirming a specific “inflammatory response” of these epithelial cells to the viral infection." (PMID 38999930, 2024). "These degradation products of RNA can activate pathogen-associated molecular patterns and endogenous damage-associated molecular patterns recognition receptors, then mediate the expression of downstream inflammatory factors (e.g., IFNB, IL1B, IL18) to resist viral infection." (PMID 38473966, 2024). "We conducted in vitro experiments to assess mitochondrial damage in cells following viral infection, measure the expression levels of the NLRP3 inflammasome and IL-1β, and evaluate the activation pathway of the NLRP3 inflammasome in PEDV-infected porcine small intestinal epithelial cells." (PMID 39728983, 2024). "Indeed, cytokines such as IL-1β, IL-6 and TNF were shown to be produced in the brain itself following peripheral viral infection, most notably by microglia." (PMID 39107476, 2024). "During viral infections, RNase L has been demonstrated to promote NLRP3 inflammasome activation through a signaling pathway involving DHX33 and MAVS, leading to the production of IL-1B in bone marrow-derived dendritic cells." (PMID 38473966, 2024). "Therefore, we studied the specific process involved in the secretion of the inflammatory cytokine IL-1β after the PEDV infection of IPEC-J2 cells, and we found that viral infection activated the NLRP3 inflammasome in this context." (PMID 39728983, 2024). "Moreover, HPV vaccines have been associated with increased levels of cytokines (IL-2, IL-6, IL-1α, and IL-1β) and with the induction of IFN-γ-producing CD4+ and CD8+ T-lymphocytes, cytotoxic cells that clear viral infections." (PMID 38068369, 2023). "Indeed, the knockdown of DUSP1 or the m6A eraser ALKBH5 enhanced the expression of innate immune response genes, including IL-1β, CSF3, TGM2, and SRC, during bacterial or viral infections." (PMID 36625590, 2023). "The screening revealed that knocking down Rpsa robustly repressed HSV-1-induced expression of Il1b, the typical anti-viral cytokine, as well as a set of proinflammatory cytokines genes, suggesting RPSA as an important molecule in virus infection-triggered innate inflammatory response." (PMID 38114488, 2023). "In contrast to IL-1β mRNA (for which HMPV inhibited the induction by LPS), we observed an additive effect of HMPV preinfection on LPS-stimulated IFN-β mRNA levels, an effect that became apparent at 6 to 18 hours post viral infection." (PMID 37435074, 2023). "Viral infections can trigger IL-1β expression by activating the NLRP3 inflammasome or MAPK signaling pathway, while different viruses may induce IL-1β expression through different signaling molecules." (PMID 35854395, 2022). "In addition, the expression of four immune-related genes, TRAF3, IL-1β, TNF-α, and TLR2, was differentially altered following viral infection." (PMID 36552207, 2022). "These phenomena could be due to the fact that DVP-1 strengthened the organic immunity by stimulating the TLR4/MyD88/NF-κB signaling pathway by which more cytokines, such as IL-1β, IL-4, IL-6, and TNF-α, were generated and released before the viral infection." (PMID 36177044, 2022). "Although the NLRP3 inflammasome-mediated IL-1β production plays an essential role in viral infection, there are no mechanism studies on SVA that induce NF-κB and NLRP3 activation in vitro or in vivo." (PMID 35254168, 2022).
viral infection (continued). "The viral infection also led to common alterations in some genes and signaling pathways in both iM1φ and iM0φ cells, such as IL1A, IL1B, CCL7, chemokine-mediated signaling, viral protein interaction with cytokine–cytokine receptor, and Toll-like receptor signaling." (PMID 35440562, 2022). "In contrast to viral infection alone, we detected a moderate, yet statistically significant increase in pro-IL-1β mRNA and IL-1β protein levels in cells co-infected with the non-mucoid PA isolate and HRV." (PMID 35265536, 2022). "In detail, TLR7 favors the production of cytokines involved in CD4+ T helper 17 (Th17) cell polarization (IL-1β, IL-6, and IL-23) after virus infection with MV and VSV, whereas TLR8 promotes the TH1-promoting cytokine response and type I IFN production after viral infection with ECMV." (PMID 36359340, 2022). "In addition to alarmins, the responses of airway epithelial cells to viral infection encompass a wide range of pro-inflammatory cytokines and chemokines, including eotaxins, RANTES, IL-17, TNF-α, IL-6, IL-8, and IL-1β." (PMID 36077310, 2022). "When nontreated ID8 and MCA205 cells were compared, higher basal levels of antiviral response genes (e.g., Cxcl10, Ifnb, Il1b) and lower basal levels of dsRNA sensor genes (e.g., Ddx58, Tlr3) were observed in MCA205 cells, which would limit viral infection/replication and detection, respectively." (PMID 34922008, 2022). "In particular, the expression of cytokines IL-1β, IL-6, and TNF-α was higher than that of the regulatory cytokine IL-10, resembling a cytokine profile characteristic of M1 phenotype, which typically intervene in counteracting bacterial and viral infections." (PMID 36016576, 2022). "Reovirus, a dsRNA virus infection, induced a greater activation of the NLRP3 inflammasome in airway epithelial cells from EphA2-knockout mice than that in wild-type mice, which resulted in the production of IL-1β." (PMID 36077310, 2022). "During viral infection, DNA or RNA viruses that serves as PAMPs are recognized by a sensor of TLR or NLR results in the transcription and expression of the NLRP3 inflammasome, pro-IL-1β, and pro-IL-18 via NF-κβ upregulation (signal 1 or priming)." (PMID 34638790, 2021). "Although the IL-1β response module was modestly induced by SARS-CoV-2 infection, the IL-6 response module was significantly enriched in transcriptional programs induced by this viral infection." (PMID 33319166, 2021). "BCG, given 1 month prior to an infectious challenge, enhanced clearance of yellow fever vaccine strain viremia, an effect that correlated with higher pro-inflammatory cytokine production (TNF, IL-1β, IL-6) from BCG-vaccinated adult volunteers, with a crucial role for IL-1β production." (PMID 34326836, 2021). "Furthermore, while certain genes were repressed during both virus infections (e.g., Irf7 or Ifnb1), expression of others was more prominently reduced upon H5N1 infection (e.g., IL-1β, IL-6, Ccl2)." (PMID 32231671, 2020). "With H1N1 infection, human macrophages and neutrophils produced significantly higher levels of pro-inflammatory cytokines and chemokines, such as TNF-α, IL-1β, IL-6, and fractalkine, compared to that with no virus infection." (PMID 32901688, 2020). "Thus, the increase in IL-1β and RANTES levels by VitD3 is important as this enhances clearance of viral infections such as RSV by recruiting T cells and monocytes to the site of infection." (PMID 32318074, 2020). "Furthermore, inflammatory responses induced by various microbial and viral infections led to the production of pro-inflammatory cytokines such as TNF-α, IL-6, and IL-1β in macrophages via upregulation of the PI3K/AKT and MAPK pathways." (PMID 32867320, 2020).
viral infection (continued). "Specifically, we found that: 1) young children with high miR-155 nasal levels during viral infection had increased production of pro-inflammatory cytokines (TNF-α, IL-1β); and 2) the individuals with the highest levels of TH1 cytokine polarization had higher TNF-α and IL-1β levels." (PMID 32442188, 2020). "In addition to allowing efficient BV transduction, wtBV has been shown to immunostimulate the release of inflammatory cytokines, including INFs, TNF-α, IL1A, IL1B and IL6 in mammalian cells and confer protection from lethal virus infection in mice." (PMID 31649751, 2019). "While a significant upregulation was detected for IL-6 and IL-1β, The effect was apparently not specific for the virus infection, as it was also evident in the mock-infected co-culture, albeit lower than the influenza-infected group." (PMID 30467502, 2018). "Herein, we report on the role of osteopontin (OPN) in regulation of RSV infection in human epithelial cells and how interleukin-1 beta (IL-1β), a cytokine secreted soon after RSV infection, when persistently expressed can induce OPN expression leading to increased viral infection." (PMID 29677209, 2018). "Neither NIH 3T3 or 3T6 Swiss albino secrete IL-1β or oncostatin M at baseline or after virus infection." (PMID 29543735, 2018). "Following viral infection or transfection with foreign DNA, CARD9 directly interacts with Rad50, a cytosolic DNA sensor, and these CARD9-Rad50 complexes subsequently recruit BCL10 to promote IL-1β secretion." (PMID 30127791, 2018). "When the expression of caspase-1 was inhibited by caspase-1 siRNA, the infection of CVB3 or EV71 failed to elicit the elevated maturation of both IL-1β and IL-18, indicating that the maturation of both cytokines depends on caspase-1 during viral infection." (PMID 29440739, 2018). "Blocking IL-1β activity reduces the virus-induced expression of fibrinogen-like protein-2 (FGL2) in macrophages, and limits the liver recruitment of CD45+Gr-1high neutrophils upon the virus infection." (PMID 26367131, 2015). "IL-1β driven neutrophilia was mediated by IL-17A in the initial phase of viral infection, but became independent of IL-17A during the peak phase of viral replication." (PMID 24918427, 2014). "This downregulation is particularly surprising for IL1B, which is considered a type I IRG and therefore one might expect it would be upregulated during viral infection." (PMID 24465555, 2014). "As a major transcription factor for antiviral and immune stimulatory activities, NF-κB is thought to play an important role in the induction of pro-inflammatory molecules, such as interleukin-1β (IL-1β), and tumor necrosis factor α (TNF-α), upon cellular responses against a virus infection." (PMID 25699183, 2014). "They suggested that IL-1β may enhance IgM antibody responses and the recruitment of CD4+ T cells to viral infection sites." (PMID 24676272, 2014). "As indicated in the results, the production of IFN-α, IFN-β, IL-1β, IL-6 and TNF-α of PAMs is improved highly after CSFV Shimen strain infection, supposing the cells might use this way to defense the virus infection and to protect the host from harm." (PMID 24034559, 2013). "Although administration of IL-1β promotes the pathogenesis of TMEV-induced demyelinating disease, the IL-1β produced via NLRP3 proteosome activation upon viral infection is considered to be a protective mechanism against microbial infections by promoting the apoptosis of infected cells." (PMID 22985464, 2012). "During the first 1–4 day after virus infection, virus are replicated in cardiac myocytes and trigger innate immune signaling, which contribute to the increasing expression of pro-inflammatory cytokines including TNF-α, IL-6, IL-1β and chemokines." (PMID 23029542, 2012).